SLC3A2 (solute carrier family 3 member 2)
Diseases named in the same sentence as SLC3A2 in open-access papers (continued):
Sharing a sentence is not in itself a finding about the gene and the disease.
cancer (149 papers, 2004 to 2026). A tumor composed of atypical neoplastic, often pleomorphic cells that invade other tissues. "SLC3A2's expression patterns across various cancers have been linked to poor patient outcomes, suggesting its role in oncogenic signaling pathways." (PMID 38977800, 2024). "The increased expression of SLC3A2 has been associated with the initiation and advancement of various forms of cancer because of its wide range of molecular activities." (PMID 39807126, 2024). "Elevated levels of SLC3A2 are linked to the emergence, metabolic activity, and advancement of several cancers, particularly lung, breast, squamous cell carcinoma of the head and neck, and liver cancers." (PMID 38977800, 2024). "Owing to these diverse molecular functions, overexpression of SLC3A2 has been found associated with the development and progression of various types of cancer." (PMID 37484811, 2023). "Intriguingly, only in STES and STAD, SLC3A2 mutations corresponded to reduced transcriptomic levels, which was possibly attributed to the low mutated rate in other types of cancer." (PMID 35992269, 2022). "The results demonstrated that SLC3A2 was significantly associated with PDL1 overexpression in most cancers, even in the merged cohort (r = 0.21, p < 0.0001)." (PMID 35992269, 2022). "The total mutation rate of SLC3A2 ranged from 0.7 to 6.6%, in which missense variation was the most common variation of SLC3A2 across cancers." (PMID 35992269, 2022). "While the role of SLC7A11 in cancer biology has been studied widely in recent years, few studies have focused on the effect of SLC3A2 during tumorigenesis and its association with patients’ prognosis." (PMID 35992269, 2022). "Among the cancer types analyzed, SLC3A2 was associated with prognosis in 15 cancers, where in 93.3% (14/15) of the cases, SLC3A2 over expression was correlated with poor OS." (PMID 35992269, 2022). "We identified the target of the SF-25 clone as the tumor-associated antigen SLC3A2, a cell surface protein with key roles in cancer metabolism." (PMID 34112739, 2021). "Xc- consists of the light-chain subunit xCT (SLC7A11) and a heavy-chain subunit (4F2hc/SLC3A2).11 xCT expression is increased in several cancers, and is associated with drug resistance and poor survival." (PMID 27421095, 2016). "Here, we conducted a bioinformatic study at pan-cancer level to systematically explore whether the intra-tumoral expression of SLC3A2 is associated with patients’ survival and its potential value in immunotherapy." (PMID 35992269, 2022). "Overall, the landscape of gene mutation in samples with high and low SLC3A2 expression was different, which may be explained by distinct drive genes for each cancer." (PMID 35992269, 2022). "Similarly, SLC3A2 correlated with shorter DSS in 9 cancers, while only in KIRC it was associated with prolonged DSS." (PMID 35992269, 2022). "Given that SLC3A2 is associated with patients’ prognoses in multiple cancer types, we questioned whether SLC3A2 directly affects cell proliferation ability." (PMID 35992269, 2022). "In this context, SLC3A2 expression level may be associated with the remodeling of microenvironment in cancers." (PMID 35992269, 2022). "Third, we explored the association between SLC3A2 expression and potential response to immunotherapy at a pan-cancer level, which has an important reference value in judging patients’ condition, estimating prognosis, directing treatment, and evaluating the curative effect." (PMID 35992269, 2022). "To explore the relevance between SLC3A2 and the genetic landscape in each cancer, we first investigated whether the SLC3A2 mutation itself could affect its mRNA expression." (PMID 35992269, 2022). "The altered expression of these cancer associated genes might involve in the modulation of metastasis by SLC3A2 in GC cells." (PMID 29179459, 2017).
cancer (continued). "The investigation into the anti-cancer potential of ginsenosides targeting SLC3A2 has yielded significant insights, aligning with and extending existing research in cancer therapeutics." (PMID 40566559, 2025). "The SLC7A11/SLC3A2 complex (system Xc−) is a cystine/glutamate antiporter that is frequently overexpressed in cancer cells, including oral cancer." (PMID 40362545, 2025). "Given the significant role of the TME in cancer progression and its impact on prognosis, we combined various datasets to investigate the distribution of SLC3A2 expression within the TME." (PMID 39926285, 2025). "Experimental studies are recommended to confirm these in silico findings and fully explore the anti-cancer benefits of ginsenosides in relation to SLC3A2." (PMID 40566559, 2025). "This overexpression was associated with enhanced tumourigenesis via the MEK/ERK signaling pathway, underscoring the importance of SLC3A2 in cancer cell proliferation and survival." (PMID 41154605, 2025). "Overexpression of SLC3A2 promotes anchorage-independent cell growth, tumorigenesis, and activation of integrin-regulated signaling pathways, making it a critical player in cancer progression." (PMID 40597436, 2025). "Utilizing MD as a pivotal technique in computer-aided drug discovery, first, the binding efficacy of 128 ginsenosides against SLC3A2 was evaluated, as this protein is highly and consecutively expressed in all cancers." (PMID 40566559, 2025). "LAT1 (SLC7A5/SLC3A2) is broadly upregulated in rapidly proliferating tissues and many cancers, whereas LAT2 (SLC7A8/SLC3A2) exhibits wider expression in normal epithelia." (PMID 40507232, 2025). "Specifically, studies should focus on evaluating the inhibitory effects of ginsenosides on SLC3A2 activity in various cancer cell lines and animal models to confirm their efficacy and safety profiles." (PMID 40566559, 2025). "We further demonstrate that c‐Myc–IRP2–IRE axis is responsible for the upregulation of RTN4IP1, and identify SLC1A5, SLC3A2, and SLC7A5, three amino acid transporters implicated in cancer, as essential downstream effectors of RTN4IP1 in ESCC." (PMID 39757767, 2025). "SLC3A2 is overexpressed in several cancers, including prostate cancer, bladder cancer, papillary thyroid carcinoma, colorectal carcinoma, and gastric cancer, where its upregulation is linked to worse patient outcomes." (PMID 40597436, 2025). "A high level of SLC3A2 increases cancer cell proliferation, invasion, and migration, while its knocking down increases apoptosis in cancer cells." (PMID 38705513, 2024). "The levels of GPX4, SLC7A11, and SLC3A2 were reduced in cancer cells treated with either BRD4 knockout or JQ-1." (PMID 38565708, 2024). "Beyond its intrinsic effect on cancer cell proliferation, SLC3A2 increases the stiffness of the TME and augments the capacity of cells to respond to matrix rigidity." (PMID 38705513, 2024). "An analysis across various cancer types highlighted a consistent increase in SLC3A2 mRNA levels, including in READ, TGCT, and HNSC." (PMID 38977800, 2024). "SLC3A2 is essential for regulating ferroptosis, apoptosis, and proliferation in cancer cells by interacting with XCT." (PMID 39807126, 2024). "We then found that after MLN4924 treatment, SLC7A11 levels were remarkably increased in time- and dose-dependent manners in multiple lines of cancer cells, while the SLC3A2 levels were increased moderately in a cell line–dependent manner." (PMID 38959043, 2024). "The disulfidptosis genes: NCKAP1, LRPPRC, SLC7A11, OXSM, SLC3A2, NDUFS1, and GYS1 occurred somatic mutations in pan-cancer, with 1 % SNV frequency." (PMID 39605832, 2024). "SLC3A2 has similarly been shown to regulate proliferation, migration, and therapy resistance in cancer cells." (PMID 38542265, 2024).
cancer (continued). "Amplifications in genes such as SLC3A2, OXSM, and GYS1 were linked to increased expression in cancer tissues, whereas genes such as NDUFS1 and NCKAP1 showed reduced expression, underscoring the diverse impact of DRG expression on BLCA pathology." (PMID 38507521, 2024). "Research showed that SLC3A2 promotes cancer cell proliferation and confers a poor prognosis for various cancer types." (PMID 38968580, 2024). "We found that the expression of GYS1 and SLC7A11 were upregulated, while those of NCKAP1, NDUFS1, NUBPL, OXSM, RPN1, and SLC3A2 were downregulated in ccRCC tissues compared with those in the para-carcinoma tissues." (PMID 38271056, 2024). "Immune cells among TME are associated with the hallmarks of BC 3, we continued to evaluate the biomarker relevance of SLC3A2 compared to standardized cancer biomarkers in immune checkpoint blockade sub-cohorts using TIDE database." (PMID 37484811, 2023). "During cancer immunostimulation, the secretion of TNF downregulates the expression of SLC7A11 and SLC3A2, and reduces the absorption of cysteine, leading to lipid peroxidation and iron deposition in cancer cells." (PMID 37681908, 2023). "Overexpression of HML-2 is associated with tumorigenesis and neurodegeneration, similar in this regard to overexpressing of SLC3A2 in cancers more widely." (PMID 37918802, 2023). "For this purpose, SLC3A2 siRNA and the anti-cancer alkaloid camptothecin were co-loaded into SLC3A2 Fab-functionalized nanoparticles." (PMID 36770817, 2023). "SLC3A2 is a key chaperone for xCT in the process of ferroptosis, metabolism and proliferation in cancer cells 31-33." (PMID 37484811, 2023). "With the increase of cancer stage and nodal metastasis status, SLC3A2 gene promoter methylation level continued to rise." (PMID 37484811, 2023). "The amino acid transporter LAT1 (SLC3A2/SLC7A5) is a kind of cancer cell-specific transporter expressed in various sources of cancer, and the high expression level of LAT1 is closely related to the poor prognosis of patients." (PMID 37699892, 2023). "Initially, we analyzed the relationship between 150 immunoregulatory factors and SLC3A2 in each cancer type." (PMID 35992269, 2022). "In this context, it is plausible for SLC3A2 to maintain the proliferative phenotype of cancer cells in vivo." (PMID 35992269, 2022). "For some cancers, SLC3A2 showed increased expression in cancer regions compared with normal tissues." (PMID 35992269, 2022). "We also report a function for the SCRIB/LLGL polarity complex in cancer cells as a regulator of membrane trafficking of the SLC7A5/SLC3A2 amino acid transporter complex." (PMID 35501367, 2022). "Here, we conducted a pan-cancer level study to systematically analyze the role of SLC3A2 in patients with cancer." (PMID 35992269, 2022). "We used public databases to investigate the expression of SLC3A2 in cancer tissues and its relationship with the prognosis of cancer patients." (PMID 35057861, 2022). "In conclusion, this pan-cancer level bioinformatic study systematically elucidated the role of intra-tumoral expression of SLC3A2 in the survival of cancer patients and potential immunotherapeutic response." (PMID 35992269, 2022). "We analyzed the correlation between SLC3A2 and stromal, immune, and estimation scores for every cancer." (PMID 35992269, 2022). "In most cancers, as classical immunostimulators, CD40LG and TNFSF14 were negatively associated with SLC3A2." (PMID 35992269, 2022). "Our study was the first to comprehensively analyze the role of SLC3A2 at pan-cancer level, which provided many valuable and integrated advice for the selection of appropriate cancer types." (PMID 35992269, 2022). "The effect of SLC3A2 on the proliferation and drug resistance of cancer cell lines was evaluated by DEPMAP." (PMID 35992269, 2022). "In previous studies, the glutamine transporters SLC1A5, SLC7A5, SLC7A11, and SLC3A2 were found to be highly expressed in a variety of cancers." (PMID 34573287, 2021).
cancer (continued). "Several previous studies have shown that SLC7A5 and SLC3A2 are prognostic markers in different types of cancer." (PMID 32093034, 2020). "In the Human Protein Atlas 2 CD98hc (gene name / entry: SLC3A2) shows broad expression in healthy tissues as well as cancers, predominantly as an unfavorable prognostic marker." (PMID 32089738, 2020). "In vitro experiments were conducted to investigate the effect of SLC7A5/SLC3A2 knockdown in the proliferation of cancer cells and to the sensitivity to tamoxifen." (PMID 32093034, 2020). "Solute carrier family 3 member 2 (SLC3A2) has been reported to be highly expressed in a variety of carcinomas." (PMID 29179459, 2017). "Proliferation, and tumor volume and weight were analyzed for cancer cells ectopically expressing SLC3A2, NRG1 and SLC3A2-NRG1." (PMID 27626312, 2016). "The MD and molecular dynamics simulations revealed a strong affinity and stability of ginsenoside–SLC3A2 complexes, suggesting a potent mechanism through which these natural compounds could exert anti-cancer effects." (PMID 40566559, 2025). "Several studies in recent years have extensively investigated the function of the disulfidoptosis-related SLC7A11 gene in cancer, but the role of its partner protein, SLC3A2, remains unknown unclear in NPC." (PMID 39926285, 2025). "This understanding underscores the importance of SLC3A2 as a novel prognostic marker and a potential therapeutic target, particularly in immunotherapy strategies, highlighting its significance in the broader context of cancer treatment." (PMID 38977800, 2024). "Also, in LUAD, Homeo box A13 (HOXA13) which is a transcriptional factor augments SLC3A2 expression in increasing cancer progression." (PMID 38705513, 2024). "Furthermore, we found upregulated SLC3A2 mRNA expression in 14 types of human cancer compared with normal human tissues." (PMID 37484811, 2023). "With the increase of cancer stage and nodal metastasis status, SLC3A2 expression continued to rise." (PMID 37484811, 2023). "Overexpression of SLC3A2 may lead to an increase in glucose uptake and metabolism, which could provide cancer cells with the energy required for their survival and proliferation." (PMID 38253025, 2023). "The copy number variation well reflected the transcriptomic level of SLC3A2 in most cancer types." (PMID 35992269, 2022). "First, SLC3A2 is a promising anti-cancer target in the future." (PMID 35992269, 2022). "More interestingly, PDT activates T lymphocytes to release IFN-γ which has been proved to downregulates both system xc- subunits (SLC3A2 and SLC7A11) at the transcriptional level, thereby causing depletion of the intracellular GSH pool and triggering ferroptosis in cancer cells." (PMID 35645842, 2022). "We found that the expression of SLC3A2 in cancer tissues is higher than that in normal tissues, and is related to the poor prognosis of cancer patients, which suggests that targeting SLC3A2 may bring clinical benefits in cancer patients." (PMID 35057861, 2022). "In addition, SLC3A2 expression level was related to the remodeling of the immune microenvironment in cancers and some immune checkpoints such as PD-1 and PD-L1, which were potential therapeutic targets in many distinct cancers." (PMID 35992269, 2022). "On the contrary, SLC3A2 was positively correlated with immune infiltrates in PRAD and PCPG, which suggested that SLC3A2 may play distinct roles in different cancer types in terms of immune cell recruitment." (PMID 35992269, 2022). "The results showed SLC3A2 is upregulated in 67.6% (23/34) cancers, such as LGG, GBM, and UCEC." (PMID 35992269, 2022). "Therefore, it is imperative to explore the expression and clinical relevance of SLC3A2 in different cancer types." (PMID 35992269, 2022).
cancer (continued). "SLC3A2 can also be used as a prognostic marker for human cancers." (PMID 36358610, 2022). "To explore whether SLC3A2 exerted an effect on the survival interval of patients with cancer, we correlated SLC3A2 expression with patients’ OS, DSS, and DFI." (PMID 35992269, 2022). "SLC3A2 silencing in cancer cells reverts tumorigenesis, migration, and proliferation." (PMID 36358610, 2022). "Therefore, it is important to consider the role of SLC3A2 in immunotherapy in distinct cancer types." (PMID 35992269, 2022). "Furthermore, we found SLC3A2 methylation in LUSC cancer tissues using bioinformatic analysis, and this was validated in both LUSC and LUAD cells." (PMID 36358610, 2022). "Specifically, anti-PD-L1 antibodies stimulate CD8+ T cells to release cytokine IFNγ to activate the JAK-STAT1 pathway in cancer cells, thereby reducing the expressions of SLC7A11 and SLC3A2, and ultimately increasing the sensitivity of cancer cells to ferroptosis." (PMID 34796174, 2021). "Interestingly, in melanoma patients that benefit from immunotherapy, a higher T cell infiltration, as well as an increased release of IFN-γ, correlate with low expression of SLC3A2 gene in the relative cancer cells." (PMID 33540645, 2021). "In addition, we found that silencing of both SLC7A5 and SLC3A2 by RNA interference impaired the proliferation of the ER+ cancer cells." (PMID 32093034, 2020). "Furthermore, BRD4 expression was positively related to GPX4, SLC7A11, and SLC3A2 expression in pan-cancer patients." (PMID 30988278, 2019). "Given the central regulatory function of SLC3A2 and the increasing interest in plant-derived anti-cancer agents, exploring the binding potential of ginsenosides to SLC3A2 may provide new insights into natural ligand-based inhibition of amino acid transporters in cancer." (PMID 40566559, 2025). "Additionally, an analysis of cancer stages revealed a significant correlation between the expression levels of SLC3A2, BSG, SLC7A5, SLC7A6, LCN2, and SLC7A9 and the pathological stages of ACC, with p-values of 0.28, 0.468, 0.00799, 0.0237, 0.0359, 0.264, 0.193, 0.81, and 0.0246, respectively." (PMID 40566559, 2025). "However, in a variety of cancer lines, JQ-1 has been reported to promote erastin-induced ferroptosis by downregulating a number of genes associated with this process, such as SLC7A11, SLC3A2, and GPX4." (PMID 40695797, 2025). "In addition to activating mTORC1, SLC7A5 can also facilitate MYC and EZH2 signaling in cancer cells, while SLC3A2 has also been confirmed to facilitate uncontrolled proliferation of cancer cell through AKT, MAPK, and cell cycle-related P21/P27 signaling pathways." (PMID 38267663, 2024). "Additionally, SLC3A2 was more highly expressed in 18 different types of cancers." (PMID 38968580, 2024). "Consequently, the overexpression of SLC3A2 contributes to radiotherapy resistance in tumors, indicating that SLC3A2 could surface as a promising clinical prospect in cancer treatment." (PMID 37799714, 2023). "Notably, SLC3A2 was significantly associated with higher TMB, MSI, and neoantigen in THYM, which meant more events of immunosurveillance would appear in this type of cancer." (PMID 35992269, 2022). "In addition, iron death plays a role in the anti-cancer effects of SLC3A2 in vivo and in vitro." (PMID 35057861, 2022). "In addition, SLC3A2 could also serve as a target for CAR-T therapy given its overexpression on the membrane of cancer cells." (PMID 35992269, 2022). "Additionally, immunotherapy activated CD8+ T cells can induce ferroptosis in cancer cells by interferon gamma-mediated downregulation of the two subunits of system Xc−, solute carrier family 7 member 11 (SLC7A11) and SLC3A2, leading to a decrease in the antioxidant capacity of cancer cells." (PMID 33499222, 2021).